AR (androgen receptor)
Diseases named in the same sentence as AR in open-access papers (continued):
Sharing a sentence is not in itself a finding about the gene and the disease.
prostate carcinoma (continued). "This notion is also further emphasized by the fact that all targeted therapies in prostate cancer treatment are directly aimed in a functional inhibition of AR activity." (PMID 26412853, 2015). "The proliferative role of TRPM8 in cancer cells is also demonstrated in AR+ prostatic carcinoma (LNCaP), osteosarcoma (MG-63 and U2OS), and colon cancer (Caco-2) cell lines." (PMID 26512697, 2015). "Detailed mechanistic insights indicated that full length AR undergo heterodimerization with an ARΔLBD in androgen depleted prostate cancer cells." (PMID 25705125, 2015). "Androgen receptor (AR) plays a critical role in the development and progression of prostate cancer (PCa)." (PMID 25852559, 2015). "They focused their attention to response elements in promoters or enhancers recognized by known transcription factors having a role in prostate cancer, primarily androgen receptor and in a prostate cancer cell line, LnCaP cells." (PMID 25658610, 2015). "Variant identification also significantly enhances the utility of the PTEN null prostate cancer model both in terms of understanding the function of AR and as a system for assessing therapies targeting resistant forms of the androgen receptor." (PMID 26196517, 2015). "At the time of censure, the median prostate cancer specific survival for patients with low stromal AR was 622 days, which was significantly less than patients with high stromal AR expression at 2528 days (p=0.013)." (PMID 25965833, 2015). "In prostatic carcinoma, cytoplasmic GOLPH3 was associated with Gleason score, stage and androgen receptor (P = 0.034, P < 0.001, and P = 0.008 respectively)." (PMID 28983350, 2015). "More recently, preclinical models have demonstrated that the AR antagonist ODM-201 is able to inhibit F877L prostate cancer mutant cell growth." (PMID 26566796, 2015). "Androgen receptor (AR) is the most important protein in the development and progression of prostate cancer." (PMID 25893082, 2015). "Recent study shows that Hsp90 and its co-chaperone FKBP51 also promotes hormone-independent nuclear localization of androgen receptor in prostate cancer cells and thereby plays a critical role in progression of prostate cancer." (PMID 25973397, 2015). "Future studies are needed to determine the effect of α-tomatine combined with curcumin on AR signaling in androgen-dependent prostate cancer cells." (PMID 26630272, 2015). "Further functional characterization suggests that PABPC1 plays an important role in modulating AR nucleocytoplasmic localization and function in prostate cancer cells." (PMID 26176602, 2015). "Ligand-induced AR phosphorylation at Ser-81 was also notably repressed in Mahanine treated prostate cancer cells." (PMID 25705125, 2015). "The potential role of AR-Vs in driving prostate cancer progression is supported by several independent correlative clinical studies describing the significant association of AR-Vs with advanced disease progression and a shorter survival period." (PMID 25481872, 2015). "Particularly, in prostate cancer, the deacetylation of AR by SIRT1 represses androgen-induced AR transcription and contributes to AR-induced tumorigenesis." (PMID 25705129, 2015). "The interplay between Jarid1b and AR on AR transactivation has been described in prostate cancer cells where Jarid1b is found up-regulated." (PMID 26151052, 2015). "Like the mouse cortex/hippocampus, 22Rv1 cells, a human prostate carcinoma epithelial cell line, are also found to express two AR protein species of ~112 and 75–80 kDa." (PMID 26317111, 2015). "Both gene lists identified the androgen receptor as a significant upstream regulator, consistent with the known central role of the androgen receptor signaling pathway in prostate cancer." (PMID 25658610, 2015).
prostate carcinoma (continued). "Results obtained from human prostate cancer cell and tissue model together shows that AR and LMTK2 are binding partners suggesting a functional significance of LMTK2 in AR-axis." (PMID 26008968, 2015). "AR is a well-studied steroid hormone receptor that also plays a crucial role in additional diseases including androgen insensitivity syndrome and prostate cancer." (PMID 26308581, 2015). "This was believed to be the mechanism of action of taxanes in prostate cancer until recently when it was demonstrated by several groups that taxanes in fact inhibit the AR signaling pathway in prostate cancer." (PMID 26160840, 2015). "In prostate cancer, the AR facilitates cell proliferation via effects on the cyclin/cyclin-dependent kinase (CDK)/retinoblastoma (RB) pathway." (PMID 25896606, 2015). "The hormone therapy is initially effective for inhibiting the growth of prostate cancer by suppressing androgen receptor (AR) activity." (PMID 26506397, 2015). "In37, SMAD3 is experimentally demonstrated to repress the androgen receptor (AR) through MH2 domain to regulate the androgen-signaling pathway in prostate cancer cells." (PMID 26648121, 2015). "As proof of concept, we focused on polymorphisms within regulatory elements bound by two TFs, ER-α and AR, that are key nuclear receptors in common human cancers characterized by a genetic component to their etiology, breast and prostate cancers." (PMID 25693204, 2015). "siRNA mediated down-regulation of PCA3 significantly inhibited growth and viability of prostate cancer cells and also reduced the expression of AR target genes, suggesting it can be a potential therapeutic target." (PMID 26082843, 2015). "miR-130a, jointly with miR-203 and miR-205, targets several components in the MAPK and androgen receptor (AR) pathways to induce apoptosis and cell cycle arrest in prostate carcinoma cells." (PMID 25544755, 2015). "Phosphorylation of the androgen receptor (AR) hinge and ligand-binding sites by GSK3β has been reported to inhibit expression of AR gene targets, thus inhibiting androgen-dependent prostate cancer cell proliferation." (PMID 25714023, 2015). "The profound effect of AR axis inhibition on prostate cancer cells has ramifications for many kinase signalling pathways, particularly those that have accumulated genomic aberration during disease progression." (PMID 25896606, 2015). "In support of this possibility, AR was shown to promote DNA DSBs to aid intra- and inter-chromosomal translocations in prostate cancer cells, one mechanism for which involved the hormone-dependent recruitment of AID." (PMID 26411678, 2015). "STAT3 is also involved in the response to tyrosine kinase inhibitors sunitinib and axitinib, in patients with metastatic renal cell carcinoma, and to second-generation androgen receptor inhibitor enzalutamide in patients with advanced prostate cancer." (PMID 28031890, 2015). "Combined PI3K and AR pathway inhibition gave profound tumor regressions in preclinical models of prostate cancer." (PMID 26506516, 2015). "The androgen receptor (AR) is a key transcription factor in the initiation and progression of prostate cancer (PC) and is a major therapeutic target for the treatment of advanced disease." (PMID 26462181, 2015). "We found that OTUB1 plays a critical role not only in the AR-dependent but also AR-independent cell invasion of prostate cancer cells in vitro and in vivo through the modulation of RhoA activity." (PMID 25623341, 2015). "It should be noted however, the mechanism of anticancer activity reported in the previous study pertains to unique phenotype of prostate cancer, and the cytotoxicity was clearly due to induction of apoptosis and inhibition of androgen receptor transcription." (PMID 25945840, 2015).
prostate carcinoma (continued). "Earlier studies have validated that AR splice variants, especially the most dominant variant AR3 which lacks a portion of ligand binding domain contributes to the transition of prostate cancer from androgen dependent to castration resistance." (PMID 25605250, 2015). "In analogy to its role in ERα signaling, MACROD1 interacts with and stimulates the transcriptional activity of the androgen receptor (AR) and in AR responsive prostate cancer cells, MACROD1 is needed for cell proliferation stimulated by testosterone." (PMID 26426055, 2015). "These AR-interacting proteins participate in multiple biological pathways (including prostate cancer), and are indicative of the critical role that AR plays in regulating diverse biological pathways." (PMID 26295410, 2015). "In the AR+ prostatic carcinoma and osteosarcoma cell lines, anti-TRPM8 siRNA reduced cellular proliferation and impaired cell cycle progression with arrest in the G0/G1 phases." (PMID 26512697, 2015). "Epibrassinolide (EBR) is a member of the brassinosteroids (BR) with notable activity against LNCaP prostate cancer cells expressing functional AR." (PMID 25705125, 2015). "Androgens and the androgen receptor (AR) also drive the progression of prostate cancer, although the disease is often diagnosed at an age when the serum level of testosterone in men is declining." (PMID 25436982, 2015). "The studies reported here, evaluate the effect of TCDD exposure on androgen receptor (AR) expression and activity in androgen-sensitive LNCaP and castration-resistant C4-2 prostate cancer cells." (PMID 26154658, 2015). "Currently, prostate cancer is treated with a combination of radiotherapy, chemical castration, androgen receptor (AR) antagonists (hydroxyflutamide, bicalutamide), or inhibitors of steroidogenesis (abiraterone)." (PMID 26124925, 2015). "Nevertheless, deregulation of the androgen receptor (AR) pathway has been implicated in benign and malignant prostate disorders, such as benign prostatic hypertrophy (BPH) and prostate cancer." (PMID 25826409, 2015). "Our data demonstrate that FKBP52 promotes β-catenin interaction with AR and is required for β-catenin co-activation of AR activity in prostate cancer cells." (PMID 26207810, 2015). "AR depletion resulted in decreased CIP2A protein expression in both the AR-positive prostate cancer cell lines." (PMID 25965834, 2015). "In summary, we identified a biochemical and functional link between miR-190a, YB-1 and AR signaling in prostate cancer." (PMID 26314494, 2015). "The two ETS factors ERG and ETV1 reprogram the androgen receptor cistrome with consequences for androgen ablation therapy in prostate cancer." (PMID 26462019, 2015). "Prostate cancer (PCa), the most commonly-diagnosed malignancy in males, is characterised by its dependence on androgen receptor (AR) signalling." (PMID 26501081, 2015). "Treatment of AR-positive prostate cancer LNCaP cells with resveratrol induces a decrease in receptor levels that is more pronounced at the highest concentration used of 150 μM." (PMID 26456774, 2015). "Knockdown of PABPC1 decreased AR transcriptional activity and also reduced nuclear AR in C4-2 prostate cancer cells." (PMID 26176602, 2015). "But despite clinical implementation of these improved inhibitors of AR signaling, response is partial and temporal and tumors inevitably progress into a more aggressive and typically lethal form of prostate cancer." (PMID 26412853, 2015). "Bicalutamide was found to inhibit androgen-independent prostate cancer cell growth appeared through AR-independent pathways." (PMID 25971429, 2015). "Another study indicated that ShRNA-mediated knockdown and pharmacological inhibition of GSK3 inhibited AR expression and its transcriptional activity in prostate cancer cells." (PMID 25714023, 2015). "Prostate cancer is an androgen receptor (AR)‐dependent malignancy at initiation and progression, therefore hormone therapy is the primary line of systemic treatment." (PMID 25241147, 2015).
prostate carcinoma (continued). "Quantitative chromatin immunoprecipitation (qChIP) assay has provided clear evidence of detachment of androgen-loaded AR from regulatory regions of these genes in Heat stressed prostate cancer cells." (PMID 25705125, 2015). "Despite this, AR isoforms remain vastly understudied in preclinical mouse models of prostate cancer tissues being limited to two AR-Vs as reported using the Myc-CaP cell line." (PMID 26196517, 2015). "Given the key role of androgen receptor (AR) signaling in disease progression, the current conventional approach to treat prostate cancer is androgen deprivation therapy often combined with antiandrogen treatment." (PMID 26509262, 2015). "We further examined the regulation of p23 in the context of AR signalling and prostate cancer by treating LNCaP cells with 10 nM of the synthetic androgen mibolerone (Mib)." (PMID 25241147, 2015). "AR signaling in prostate cancer stroma appears therefore to alter patient outcome by maintaining an ECM microenvironment inhibitory to cancer cell invasion." (PMID 25965833, 2015). "RUNX1 expression is necessary for AR signaling and androgen-dependent prostate cancer cell proliferation." (PMID 25537508, 2015). "In summary, these studies demonstrate for the first time that HBC, which binds exclusively to CaM, inhibits AR activity and suppresses the proliferation of both androgen-sensitive and castration-resistant AR-positive prostate cancer cells." (PMID 25704883, 2015). "It has been shown that within prostate cancer cells, wild-type AR physically interacts with Nemo-like kinase (NLK) and that NLK is able to regulate the activity and transcription of AR in this context." (PMID 26308581, 2015). "In prostate cancer, resistance to ADT is frequently associated with the emergence of androgen-independent splice variants of the AR (AR variants, AR-Vs) that lack the LBD and are constitutively active." (PMID 26554309, 2015). "Recently, in prostate cancer cells where the role of AR signals had been extensively studied, AR was found to function as a coactivator of ELK1." (PMID 26342199, 2015). "In this study, we demonstrate for the first time that AR stimulates integrin-dependent prostate cancer invasion by stimulating Src activity through a ligand-dependent but non-nuclear mechanism." (PMID 25730905, 2015). "These upstream regulators point to the importance of genes that function in the androgen receptor, hedgehog, and Wnt/β-catenin signaling pathways in prostate cancer biology." (PMID 25658610, 2015). "Elevated expression of PABPC1 in prostate cancer specimens is likely to play an important role in prostate carcinogenesis by enhancing AR signaling pathways." (PMID 26176602, 2015). "Blocking AR signaling pathway has been shown to trigger autophagy in AR positive prostate cancer cell lines, which is favorable for cell survival or cell death depending on the applied specific inhibitors and the cell contexts." (PMID 26473737, 2015). "MJC13 prevents hormone-dependent AR dissociation from the chaperone complex, which ultimately inhibits AR translocation to the nucleus, prostate cancer cell proliferation, and growth of prostate tumor xenografts." (PMID 26207810, 2015). "ACK1/TNK2 tyrosine phosphorylates AR at Y267 in androgen deprived conditions of prostate cancer cells." (PMID 26546517, 2015). "Prostate cancer is one of the most prevalent forms of cancer occurring in men, and its progression is dependent upon the androgen receptor (AR) signaling pathway." (PMID 26401448, 2015). "Our results, for the first time, provide compelling evidence further rationalizing the targeting strategy to disengage the functional interaction between miR-190a and AR signaling in clinical practice to treat prostate cancer." (PMID 26314494, 2015).
prostate carcinoma (continued). "However, resistance to these treatments inevitably occurs, hinting that targeting the AR pathway might not be sufficient, especially given the idea that increased crosstalk between distinct signaling pathways causes activation of AR target genes and regulatory networks in advanced prostate cancer." (PMID 26509262, 2015). "Targeting AR with AR degrader ASC-J9 led to prostate cancer suppression via the induction of autophagy in CWR22R cells." (PMID 26473737, 2015). "PABPC1 appears to play important roles in AR function in both androgen-sensitive and castration-resistant prostate cancer cells." (PMID 26176602, 2015). "In conclusion, our findings are the first evidence that LMTK2 negatively regulates AR activity in prostate cancer cells possibly by directly interacting with AR." (PMID 26008968, 2015). "Taken together, our findings identified a biochemical and functional link between miR-190a with reduced expression in advanced prostate cancer, YB-1 and AR signaling in prostate cancer." (PMID 26314494, 2015). "Skp2 interacts with pRb, Pten, androgen receptor (AR), and H-Ras in prostate cancer, and serves as a critical converging point for these genes in regulation of senescence." (PMID 26497688, 2015). "We have previously shown nuclear p23 to enhance AR activity and binding to chromatin, critical steps for AR signalling and prostate cancer development, and to be increased with tumour grade." (PMID 25241147, 2015). "EGCG also inhibited the expression of miR-21 followed by repression of androgen receptor (AR) signaling and, consequently, a reduction of prostate cancer cell growth." (PMID 25853141, 2015). "As we know, androgen deprivation therapy that removes circulating androgens or blocks the AR is a standard of care treatment for prostate cancer treatment." (PMID 25860954, 2015). "Ack1 tyrosine kinase is overexpressed in prostate cancer and promotes castrate resistant xenograft tumor growth and enhances androgen target gene expression and AR recruitment to enhancers." (PMID 25950519, 2015). "We undertook evaluation of the role of Lemur Tyrosine Kinase 2 (LMTK2) in modulating AR activity, as several Genome Wide Association Studies (GWAS) have shown a marked association of LMTK2 activity with the development of prostate cancer." (PMID 26008968, 2015). "As it was shown that leupaxin interacts and activates the androgen receptor in prostate cancer cells, a putative interaction between leupaxin and the ERs α and β in breast cancer cells was investigated using direct yeast-two-hybrid experiments." (PMID 25955236, 2015). "Genome-wide profiling studies demonstrated that the AR regulated transcriptome in CRPC is significantly different from that in ADT-naïve prostate cancers." (PMID 26009876, 2015). "In summary, our study has identified the protein tyrosine phosphatase PTPRR as an early and direct target of the androgen receptor that is rapidly repressed by androgens in prostate cancer cells." (PMID 25592066, 2015). "Androgens drive prostate cancer carcinogenesis and progression, even in androgen-independent tumors where the androgen receptor signaling remains active." (PMID 26002551, 2015). "We treated prostate cancer cells with these inhibitors to determine their impacts on AR signaling by measuring AR targeted transcription of PSA, TMPRSS2 and FKBP5 genes." (PMID 26009876, 2015). "The strong association of HOXB13 with positive ERG status expression fits well with the known role of androgen receptor activation for development of ERG fusions in prostate cancer." (PMID 25825985, 2015). "IL-6 promotes the proliferation of prostate cancer cells by activating the androgen receptor (AR), and this effect is inhibited by antiandrogens such as bicalutamide." (PMID 26252635, 2015). "Considerably enhanced tyrosine phosphorylation of AR was noted in AR8 overexpressing prostate cancer cells upon treatment with EGF." (PMID 25705125, 2015).